LEP (leptin)
Diseases named in the same sentence as LEP in open-access papers (continued):
Sharing a sentence is not in itself a finding about the gene and the disease.
non-alcoholic steatohepatitis (31 papers, 2003 to 2025). "After analyzing 33 studies with a total population of 2612 individuals (775 controls and 1837 MASLD patients), they found that patients diagnosed with MASLD or metabolic dysfunction-associated steatohepatitis (MASH) have higher levels of leptin in their bloodstream." (PMID 38255708, 2024). "Mucispirillum schaedleri has been reported to be a marker of a high-fat diet; it also positively correlates with serum levels of leptin and body fat and decreases upon dietary treatment of non-alcoholic steatohepatitis." (PMID 34836246, 2021). "WFA, a major compound of WS, is known to improve nonalcoholic steatohepatitis and exhibits antidiabetic effect by acting as a leptin-sensitizer." (PMID 32046183, 2020). "Leptin plasma levels have previously been found to be significantly elevated in patients with non-alcoholic steatohepatitis after melatonin treatment." (PMID 30424542, 2018). "In nonalcoholic steatohepatitis, leptin can upregulate CD14 expression through JAK-STAT3 signaling pathway and it has been demonstrated that CD14 can activate CD14-dependent TLR4 pathway to induce an inflammatory response." (PMID 28250578, 2017). "Similar reduction in leptin level has also been found in patients suffering from fulminant hepatic failure, hepatitis A, B and C infections, non-alcoholic steatohepatitis and tuberculosis." (PMID 21612659, 2011). "In addition, hypersecretion of free fatty acids, leptin, and inflammatory cytokines from the adipose tissue is strongly involved in the development of non-alcoholic steatohepatitis (NASH)." (PMID 37141242, 2023). "In addition, another previous study also showed that serum leptin concentrations are significantly higher in non-alcoholic steatohepatitis patients than in healthy people." (PMID 36362221, 2022). "It has been demonstrated that leptin could play an important role in the progression of nonalcoholic steatohepatitis by promoting liver lipid decomposition and increasing insulin sensitivity in the early stage." (PMID 35896788, 2022). "In addition, several studies have also demonstrated the important role of Socs3 in the pathogenesis of nonalcoholic steatohepatitis, regulating insulin sensitivity, leptin signaling, glucose metabolism, lipogenesis, and fatty liver." (PMID 25617409, 2015). "In addition, leptin-mediated neovascularization showed an effective role of leptin in the development of hepatocarcinogenesis in non-alcoholic steatohepatitis." (PMID 20723213, 2010). "Leptin-induced oxidative stress and inflammation mediated by Kupffer cells promote the progression of nonalcoholic steatohepatitis; additionally, reports have indicated that oxidative stress is the source of humoral and cellular immunological mechanisms that may contribute to NAFLD progression." (PMID 28257515, 2017). "We have demonstrated the remarkable pro-inflammatory and pro-oxidant influence of linoleic acid and leptin in human and mouse NAFLD/nonalcoholic steatohepatitis and showed that curcumin prevented the development of immunological alterations in this disease." (PMID 28257515, 2017). "Recent studies have demonstrated the mechanism of leptin-mediated upregulation of CD14 and TLR4 in nonalcoholic steatohepatitis." (PMID 26484872, 2015). "In patients and in vivo models of non-alcoholic steatohepatitis (NASH), metformin reduced leptin secretion and aminotransferase levels and decreased liver size." (PMID 23951244, 2013). "It reduced hepatocyte apoptosis, inflammation, fibrosis (but not steatosis), insulin/leptin resistance, hepatic and circulating triglyceride levels, and the progression to non-alcoholic steatohepatitis (NASH)." (PMID 25951129, 2015).
thyroid autoimmunity (29 papers, 2015 to 2025). "Fat accumulation is linked with elevated TSH levels, and excess adiposity can affect thyroid autoimmunity by increasing the levels of adipokines such as leptin and IL6, which are crucial for maintaining immune homeostasis." (PMID 40218202, 2025). "The emergence of sex differences in thyroid autoimmunity during puberty coincides with the simultaneous rise of leptin and estrogen levels." (PMID 38957249, 2024). "In our study, serum leptin levels were increased and statistically significant in mice with experimental autoimmune thyroiditis." (PMID 36339447, 2022). "A significantly higher level of leptin in women explains the difference in the incidence of autoimmune thyroid disease in both sexes." (PMID 31554206, 2019). "Adipose tissue is an active endocrine organ that secretes pro-inflammatory cytokines such as TNF-α, IL-6, and leptin, which may exacerbate thyroid autoimmunity and contribute to ovarian dysfunction." (PMID 41303060, 2025). "Elevated leptin levels, in particular, play a central role in immune regulation by modulating T-cell activation and proliferation, which can amplify immune responses and potentially drive the progression of thyroid autoimmunity." (PMID 39834468, 2024). "First, some lines of evidence had shown that adiposity increases the probability of having autoimmune thyroid diseases with an important role for a typical adipokine such as leptin as a peripheral determinant and thyroid peroxidase antibodies were more prevalent in the obese subjects." (PMID 35059043, 2022). "This may be due to the immunoregulatory effects of leptin, which could eventually result in the development of an autoimmune thyroid disease." (PMID 36401211, 2022). "As it was mentioned in the Introduction, leptin may play a role in the interaction between thyroid hormones and body composition and can be connected with thyroid autoimmunity." (PMID 34393994, 2021). "Leptin-induced inflammation and the presence of inflammatory cytokines like TNF-α and IL-6 within the thyroid gland may contribute to the development of thyroid autoimmunity." (PMID 38567309, 2024). "Serum leptin in patients with autoimmune thyroid disease was also significantly higher than those in patients without autoimmune thyroid disease." (PMID 37207234, 2023). "Secondly, leptin level was not determined in the current study; hence, the mechanisms of association between BMI and TSH levels and BMI and thyroid autoimmunity were obtained from literatures." (PMID 26273610, 2015). "But the relationship of leptin to autoimmune thyroid disease has not been fully elucidated." (PMID 36339447, 2022).
Cirrhosis (28 papers, 2004 to 2025). A chronic disorder of the liver in which liver tissue becomes scarred and is partially replaced by regenerative nodules and fibrotic tissue resulting in loss of liver function. "Serum levels of adiponectin, leptin and visfatin associated significantly with the presence of cirrhosis in HCV patients (P<0.001, P= 0.008, P <0.001; respectively)." (PMID 32212784, 2020). "In previous studies, association between the severity of cirrhosis and serum leptin levels is controversial." (PMID 15387890, 2004). "Furthermore, we observed a significant association between the serum levels of adiponectin, leptin and visfatin with the presence of cirrhosis in HCV patients." (PMID 32212784, 2020). "Our data clearly suggest that cirrhosis due to CHB or CHC is associated with higher leptin levels." (PMID 17540037, 2007). "Even leptin has also been found to be uncorrelated with the existence of cirrhosis in alcoholic liver disease." (PMID 34209386, 2021). "In our group of cirrhotic liver transplant candidates, leptin levels correlated with IR, BMI, and insulin concentrations, indicating several possible mechanisms of hyperleptinemia in the context of cirrhosis." (PMID 32092909, 2020). "Our finding of high leptin expression in patients with cirrhosis and HCC in human samples was consistent with clinical studies that found that leptin is increased in many liver cirrhosis and HCC patients." (PMID 30718259, 2019). "Various factors such as oxidative stress, altered nuclear receptors, cytokines signaling, mitochondrial / peroxisomal abnormality, hepatocyte apoptosis, and leptin resistance are responsible for progression towards inflammation and fibrosis/cirrhosis." (PMID 27099671, 2016). "Patients with CHB and definite histological diagnosis of cirrhosis (stage 6) at baseline liver biopsy had significantly higher levels of leptin compared to those with lower fibrosis stage (17436 pg/mL vs 6028.5 pg/mL, p = 0.03)." (PMID 17540037, 2007). "In this study, we investigated the relation between the severity of disease and serum leptin levels in post-hepatitis cirrhosis and the role of body composition, gender and viral aetiology of cirrhosis in this association." (PMID 15387890, 2004). "However, in alcohol-dependent patients with cirrhosis, leptin is significantly higher before liver transplantation and decreases significantly after transplantation." (PMID 33167521, 2020). "Consistent with this possibility, cirrhosis due to CHB is associated with high leptin levels, which constitute a negative prognostic factor for the response to lamivudine monotherapy in patients with CHB." (PMID 33167521, 2020). "Therefore, we can conclude that AdipoQ and leptin levels in patients with chronic hepatitis and cirrhosis have changed compared with healthy controls, which is consistent with Buechler’s conclusion." (PMID 33256658, 2020). "Indeed, our results indicate that insulin-resistant patients with cirrhosis had a higher BMI and leptin levels in comparison to insulin-sensitive ones." (PMID 32092909, 2020). "Whereas free leptin correlates with fat mass in cirrhotic patients as well as in healthy controls, bound leptin was positively correlated with energy expenditure in patients with cirrhosis." (PMID 31717529, 2019). "Inadequate appetite regulation and energy expenditure may be related to an elevation in bound leptin in patients with cirrhosis." (PMID 31717529, 2019). "We found significant upregulation of leptin in cirrhosis and HCC samples." (PMID 30718259, 2019). "In the present study we evaluated immune-inflammatory and metabolic effects of a treatment with high dose furosemide + HSS by means of analysis of changes of cytokine, natriuretic peptide, visfatin and leptin serum levels in subjects with cirrhosis and refractory ascites." (PMID 27941973, 2016).
Cirrhosis (continued). "In addition, linear regression test in the present study has shown that disease severity, which was determined by Child-Pugh classification, was the sole significant determinant of serum leptin levels in cirrhosis." (PMID 15387890, 2004). "A cytokine-leptin link hypothesis has also been suggested as a contributing factor to cirrhotic hyperleptinemia; presumably activated tumor necrosis factor-α (TNF-α) in cirrhosis can cause excessive release of leptin from adipose tissue." (PMID 17540037, 2007). "Serum leptin levels have been found higher in patients with chronic hepatitis C (CHC) and particular in those with more severe fibrosis or cirrhosis; however the results are conflicting." (PMID 17540037, 2007). "These suggest that the severity of the fibrotic lesions in LEPTIN−/− livers was most likely in the middle or advanced stage of fibrosis but not cirrhosis." (PMID 37705071, 2023). "As with NAFLD-related cirrhosis, there no clinical studies that analyze the role of leptin in NAFLD-related HCC." (PMID 34209386, 2021). "However, leptin is known to induce VEGF on HSC, contributing to the irreversibility of cirrhosis and, potentially, to NASH progression." (PMID 34209386, 2021). "This study noted that the increase in serum leptin was significantly correlated with cirrhosis (p<0.005), in patients with cirrhosis had higher serum levels of leptin than the controls, but not related to the development of HCC." (PMID 28076486, 2016). "It appears that relationship of serum leptin levels and nutritional status in post-hepatitis cirrhosis has not been fully clarified yet." (PMID 15387890, 2004). "Up to now, leptin concentration in patients with NAFLD-related cirrhosis has not been studied." (PMID 34209386, 2021). "The role of leptin in both NAFLD-related cirrhosis and HCC has never been studied." (PMID 34209386, 2021). "Indeed, some studies have reported that when BMI is considered as a cofactor, serum leptin levels were no longer correlated with the presence of cirrhosis." (PMID 33316927, 2020). "However, the study by Sadik et al19, serum leptin levels were normal in groups of patients with cirrhosis without HCC and controls, although in patients with HCC, serum levels were as high." (PMID 28076486, 2016).
hyperandrogenism (27 papers, 2010 to 2026). Excessive secretion of androgens from the adrenal glands or gonads. "Biological mechanisms such as hyperandrogenism, hyperinsulinaemia, and altered ghrelin and leptin signalling can heighten hunger, carbohydrate cravings, and appetite variability." (PMID 41409676, 2026). "In conclusion, AE and HEE of C. citratus corrected PCOS‐induced ovarian follicular atresia in rats by reducing hyperandrogenism and modulating LEP and GHRL production." (PMID 41532033, 2026). "Hyperandrogenism, IR, the reduced secretion of cholecystokinin postprandially, and leptin resistance defined by leptin receptors’ knockout in the hypothalamus have been implicated in the pathogenesis of hypothalamic dysfunction and appetite dysregulation." (PMID 38613082, 2024). "The PCOS rats demonstrated androgen excess, multiple ovarian cysts, elevated anti-mullerian hormone and leptin and decreased SHBG, adiponectin and 17-β estradiol with corresponding increase in ovarian transforming growth factor-β1." (PMID 38561673, 2024). "In our study, we found a significant correlation between BMI-SDS and leptin with androstenedione and testosterone levels, suggesting, as some authors support, that excess adipose tissue appears to be an important factor to androgen excess in these patients." (PMID 35412268, 2022). "We showed that aerobic exercise can then ameliorate the internal inflammatory state, further mitigate leptin resistance, and improve the sex hormone disorder and hyperandrogenism characteristic of PCOS rats by modulating the HPO axis." (PMID 34422044, 2021). "Overweight/obese females had higher levels of leptin and biochemical parameters of hyperandrogenism including testosterone and DHEAS and reduced sOB-R." (PMID 26180527, 2015). "Concentrations of ADPN, apelin, leptin, omentin, resistin, visfatin, and the L/A ratio were found to correlate with parameters of lipid metabolism in girls diagnosed with menstrual disorders and hyperandrogenism." (PMID 41303021, 2025). "Hyperandrogenism, chronic low-grade inflammation, and leptin resistance may thus interact to affect the occurrence and development of PCOS." (PMID 34422044, 2021). "Aerobic exercise can alleviate the internal inflammation by relieving leptin resistance and may mitigate the sex hormone disorder and hyperandrogenism in rats with PCOS by affecting the hypothalamic-pituitary-ovarian axis." (PMID 34422044, 2021). "We also wished to further investigate how chronic low-grade inflammation, hyperandrogenism, and leptin resistance interacted to lead to the occurrence and development of PCOS and the possible underlying mechanism by which aerobic exercise alleviated hyperandrogenism in PCOS." (PMID 34422044, 2021). "Hence, we herein speculated that in the pathophysiologic process of PCOS, hyperandrogenism, leptin resistance, and chronic low-grade inflammation may form a vicious cycle, but the relationships among the three are not completely clear." (PMID 34422044, 2021). "In line with our previous studies, PCOS animals showed excess body weight gain/ovarian mass, abnormal metabolic indices (fasting insulin, blood glucose and HOMA-IR), androgen excess, multiple ovarian cysts, elevated AMH and leptin and decreased SHBG, adiponectin and 17-β estradiol." (PMID 38561673, 2024).
fibrosis (26 papers, 2007 to 2025). the formation of excess fibrous connective tissue in an organ or tissue in a reparative or reactive process. "Even though the role of leptin in NAFLD pathogenesis is not fully understood, leptin levels have been recently associated with the NAFLD fibrosis score." (PMID 34025683, 2021). "To further confirm that the increase of leptin expression in LF tissue had a causal relationship with LF fibrosis, we analyzed the effect of different concentration of rhleptin on the expression of collagen I and III in LF cells." (PMID 29436483, 2018). "In conclusion, to our knowledge, this is the first paper regarding an association between leptin and LF fibrosis in patients with LSCS." (PMID 29436483, 2018). "A study with a larger representation of patients with fibrosis and a more balanced distribution across fibrotic stages would provide a better opportunity to explore the relationship of leptin in the progression of NAFLD." (PMID 38738048, 2024). "Leptin levels showed a significant difference between the three groups, with the highest levels present in fibrosis." (PMID 38738048, 2024). "This diet can act as a stimulus leading to NASH development in ob/ob mice since they cannot spontaneously proceed from NAFLD to NASH due to leptin absence, given that leptin is necessary for hepatic fibrosis development." (PMID 36555433, 2022). "The leptin and MCP-1 serum concentration were similar among patients with different stages of fibrosis or IR, although leptin was associated with SVR." (PMID 31888144, 2019). "Leptin is known to promote tissue fibrosis, while adiponectin has recently been demonstrated to be anti-fibrogenic in tissue fibrosis." (PMID 24982243, 2014). "Based on these observations, it seemed of interest to examine the effect of leptin on LF fibrosis." (PMID 29436483, 2018). "Fibrosis was also not detected since leptin deficient ob/ob mice are resistant to fibrosis." (PMID 24594481, 2014). "A meta-analysis including adults found a significant mean standarized difference in circulating leptin levels between patients with MASLD with fibrosis and patients without MASLD." (PMID 39201901, 2024). "Among pre-BS factors that may predict outcomes post-BS, those that have been found to be significant from the adipose tissue are VAT/SAT fibrosis, circulating CRP, Cd11b and IL10 adipose tissue mRNA levels, and possibly circulating leptin." (PMID 33670215, 2021). "This study aimed to investigate variations in serum leptin levels between subjects with and without fibrosis in NAFLD and to assess the predictive value of serum leptin levels in NAFLD subjects." (PMID 38738048, 2024). "This study measured the levels of serum leptin in subjects suffering from NAFLD with and without fibrosis." (PMID 38738048, 2024).